MTOR (mechanistic target of rapamycin kinase)
Diseases named in the same sentence as MTOR in open-access papers (continued):
Sharing a sentence is not in itself a finding about the gene and the disease.
tumor (continued). "The inhibition of the mTOR pathway can block this process, providing a basis for combined therapeutic strategies targeting FGF19 and mTOR, offering a new direction for tumor treatment, particularly in targeting tumor metabolism." (PMID 41328353, 2026). "Based on the molecular profile of the tumor, the patient was qualified for off-label targeted therapy with everolimus, an inhibitor of the mammalian target of rapamycin (mTOR) pathway." (PMID 42266657, 2026). "Over 90% of PDAC patients harbor KRAS gene driver mutations, which promote tumor proliferation, invasion, and immunosuppression of the tumor microenvironment through constitutive activation of downstream RAF/MEK/ERK and PI3K/AKT/mTOR signaling pathways." (PMID 41942368, 2026). "Here, it is demonstrated that while PTT enhances antitumor immunity by inducing immunogenic cell death (ICD), it paradoxically activates the oncogenic mTOR pathway, driving tumor immune evasion." (PMID 41255280, 2025). "Firstly, it regulates pro-cancer signaling pathways: activating AKT/mTOR (e.g., hepatocellular carcinoma), Wnt/β-catenin, and other pathways to promote tumor progression, indirectly forming an immunosuppressive microenvironment." (PMID 41154773, 2025). "Integrating advanced profiling techniques has enhanced our understanding of critical pathways (e.g., PI3K/AKT/mTOR) and highlighted the potential for tailored therapies targeting specific tumor characteristics." (PMID 39936948, 2025). "PI3K blockade reduces PIP3 levels, attenuating AKT/mTOR activation to impair tumor proliferation and metastasis." (PMID 40266213, 2025). "Nicotinamide mononucleotide elevates NAD + levels, activates AMPK/mTOR signaling, and induces autophagy and ferroptosis, effectively suppressing tumor growth in preclinical studies." (PMID 40781676, 2025). "In essence, mTOR senses the rewired metabolism (e.g. abundant methionine, lipids) and feeds forward to enhance vesicle trafficking plasticity– enabling the tumor to rapidly deploy pro-tumorigenic cargo externally and recycle membrane receptors internally." (PMID 40705199, 2025). "The development of the dual inhibitor XL765 (Voxtalisib) targeting both PI3K and mTOR pathways to block the compensatory response has shown a potent reduction of tumor growth in a patient‐derived GBM xenograft model." (PMID 38105543, 2025). "↓ PI3K/AKT/mTOR signaling → ↓ tumor volume, ↑ apoptosis rate, ↑ sensitivity to temozolomide treatment." (PMID 40761486, 2025). "The ability of isorhamnetin to suppress hypoxia‐induced autophagy and tumor growth in GC through PI3K/AKT/mTOR inhibition displays its potential as a therapeutic agent in hypoxic tumor environments." (PMID 40740483, 2025). "This inhibition reduces phosphorylation of AKT and mTOR, downregulating effector molecules such as 4EBP1, ultimately suppressing protein synthesis and tumour growth." (PMID 40426308, 2025). "TSC1/2 is another tumor suppressor and negative regulator of mTOR that is also frequently dysfunctional in cancers." (PMID 39796781, 2025). "It mitigates inflammatory responses and promotes tumor cell immune evasion by inhibiting the mTOR cell pathway and suppressing platelet aggregation." (PMID 40599143, 2025). "The PI3K/AKT/mTOR pathway is involved in the inhibitory effect of ascorbate on cell proliferation and tumor growth." (PMID 39990670, 2025).
tumor (continued). "Further analysis revealed that in state 5, low TCR scores and high activity of the PI3K/AKT/mTOR pathway indicated that MDSCs enhanced immunosuppressive effects, aiding tumour immune evasion." (PMID 40429821, 2025). "Previous studies have also highlighted the involvement of the PI3K/AKT/mTOR pathway in tumor angiogenesis." (PMID 39873475, 2025). "Although LKB1 is considered to be a tumor suppressor, NSCLCs with constitutively active Kras and inactivating mutations in LKB1 are highly sensitive to mTOR inhibitor." (PMID 40629079, 2025). "The observed reduction in tumor size and the ultrasound findings suggesting complete response indicate efficacy in simultaneously targeting angiogenesis, immune evasion, and mTOR signaling." (PMID 40916506, 2025). "Predictive biomarkers for mTOR inhibitor response remain an area of active investigation, given the variable efficacy of these agents across different tumor types." (PMID 40821795, 2025). "Tumor-induced mTOR-driven alterations to peritumoral neurons contribute directly to the cortical dysfunction observed in peritumoral tissue." (PMID 41301687, 2025). "SCFAs also inhibit key oncogenic pathways, including the PI3K/AKT/mTOR and NF-κB signaling cascades, thereby reducing tumor growth and survival." (PMID 40299687, 2025). "In pancreatic cancer, it inhibits the PI3K/Akt/mTOR pathway, a central driver of drug resistance and tumor growth, and enhances sensitivity to chemotherapy." (PMID 40806510, 2025). "SLC7A5 (LAT1) is also overexpressed in CRC tissue, promoting mTOR activation and tumour aggressiveness, with high expression correlating with poor survival and resistance to EGFR inhibitors." (PMID 41154605, 2025). "PI3K/AKT/mTOR signaling is a crucial regulator of cellular survival, proliferation, and growth, which is commonly overactivated in cancers, promoting tumor progression and resistance to treatment." (PMID 41155376, 2025). "The PI3K/Akt/mTOR signaling pathway is among the most frequently dysregulated pathways across cancers, contributing to tumor growth, survival and therapy resistance." (PMID 41301038, 2025). "Downregulation of these targets by miR‐21 can result in hyperactivation of the mTOR pathway, promoting tumor growth and survival." (PMID 40567015, 2025). "IL-6 and PI3K/Akt/mTOR signaling both promote an immunosuppressive tumor microenvironment that can blunt the efficacy of ICIs." (PMID 41374963, 2025). "Hyperactivation of mechanistic target of rapamycin (mTOR), often due to mutations in upstream regulators [e.g., the tumor suppressor tuberous sclerosis complex (TSC1/2)], promotes anabolic processes and tumor growth." (PMID 40547482, 2025). "In a model of rat bladder carcinogenesis, scientists showed that tetrahydroxycurcumin has a potent anti‐tumor effect that inhibits the PI3K/AKT/mTOR activation pathway." (PMID 41179371, 2025). "The role of cell death through autophagy regulated by ATG proteins and PI3K/AKT/mTOR pathway is dual: to suppress tumor and to sensitize cells to therapy." (PMID 40257494, 2025). "AXL, a member of the TAM family of RTKs, is implicated in activating survival pathways, including RAS/RAF/MAPK and PI3K/Akt/mTOR, which are critical for tumor proliferation and resistance." (PMID 39941857, 2025). "Such cytokines play significant roles in tumor progression when activating the mTOR signaling pathway, one that is essential for controlling the cell cycle and highly targeted by chemotherapeutic drugs due to its upregulation in NENs." (PMID 40361517, 2025). "Tumor cells utilize the highly expressed Smurf1 to link the growth signal to mTOR, providing an evidence for continuously coping with external pressures." (PMID 40958774, 2025). "Isovitexin reduces the levels of p-PI3K, p-Akt, p-mTOR, and Bcl-2 in tumor tissues, thereby inhibiting the migration, invasion, and EMT of cancer cells." (PMID 40949141, 2025).
tumor (continued). "Beyond COX inhibition, novel sulindac analogs such as sulindac sulfide amide (SSA; a N,N-dimethylethyl amine derivative of SS) exhibit anti-tumor activity through inhibition of the Akt (PKB)/mechanistic target of rapamycin (mTOR) pathway." (PMID 41298349, 2025). "This signaling route, similarly to the IL-10-enhancing effect of the PI3K/Akt/mTOR pathway in monocytes/macrophages, is used by tumor cells to promote immune tolerance and maintain M2 phenotype in TAMs." (PMID 40806725, 2025). "PDP1 overexpression downregulates adenosine monophosphate (AMP)-dependent protein kinase, resulting in the mechanistic target of rapamycin kinase (mTOR) activation and promoting tumor progression." (PMID 40746885, 2025). "Natural products hold promising potential to modulate tumor cell autophagy by targeting the PI3K/Akt/mTOR signaling pathway." (PMID 40861811, 2025). "The loss of PBRM1 was noted to lead to increased HIF transcription, STAT3, and mTOR signaling, thereby favoring tumor growth." (PMID 40725144, 2025). "Clinical studies have shown that when CDK4/6 inhibitors are used alone, some tumor cells can evade the inhibitory effects of the drugs by activating the PI3K/AKT/mTOR pathway, leading to the development of drug resistance." (PMID 41280894, 2025). "Current therapeutic strategies, particularly the use of mTOR inhibitors, have demonstrated significant efficacy in controlling tumor growth, reducing seizure frequency, and improving the quality of life for affected individuals." (PMID 40358185, 2025). "This microRNA also suppresses the mTOR signaling pathway, and its upregulation, when combined with mTOR inhibition, exerts a strong synergistic effect in suppressing tumor growth." (PMID 40761244, 2025). "A substantial downregulation of the PI3K/AKT/mTOR phospho-proteins was observed in the tumor cell lysate of Myricetin-treated xenografts, compared to the control." (PMID 40552278, 2025). "Sudhan and colleagues further demonstrated that treatment with everolimus, an mTOR inhibitor, was able to overcome resistance by restoring ErbB2-mutant tumor cell sensitivity to neratinib." (PMID 39908697, 2025). "Research shows that leucine promotes tumor proliferation by activating the mTOR signaling pathway and enhancing mitochondrial biogenesis and function." (PMID 41347169, 2025). "In contrast, the highly immunogenic and microbially influenced colorectal environment appears to shift FABP5 activity towards mTOR-mediated autophagy and anti-tumor effects." (PMID 40717587, 2025). "The aberrant activation of the PI3K/Akt/mTOR pathway in OSCC promotes tumor growth, survival, and resistance to apoptosis, alongside facilitating angiogenesis and metastasis 10,11." (PMID 39781358, 2025). "The PI3K/AKT/mTOR signaling pathway plays a central role in regulating cell proliferation, survival, metabolism, and transcription and is a critical network in tumor development and progression." (PMID 40725100, 2025). "The molecular heterogeneity of TNBC such as the accumulation of tumor mutation burdens and the activation of pathways like NF-κB, PTEN/PI3K/AKT/mTOR, JAK/STAT, and RTKs, contributes to chemoresistance and tumor progression." (PMID 40783744, 2025). "ITGA10 transmitted specific signals through TRIO and RICTOR, activating RAC/PAK and AKT/mTOR pathways to promote tumor cell survival." (PMID 40258773, 2025). "High miR-205 in OC promotes M2 macrophage polarization via PTEN/PI3K/AKT/mTOR pathway, enhancing tumor progression and poor prognosis." (PMID 41280929, 2025). "It inhibits tumor initiation and development by affecting phosphatidylinositide 3-kinase (P13K)/Akt/mammalian target of rapamycin (mTOR)/NF-kB signaling pathways." (PMID 39926108, 2025). "PRMT6 promotes EMC cell migration and proliferation by activating the AKT/mTOR signaling pathway, thereby contributing to tumor progression." (PMID 41154773, 2025).
tumor (continued). "Simultaneously, it promotes the activation of the PI3K/AKT/mTOR signaling pathway, thereby driving tumor cell proliferation and growth." (PMID 40809844, 2025). "FABP5 promotes tumor progression in pancreatic neuroendocrine neoplasms by regulating lipid metabolism and the mTOR signaling pathway." (PMID 40717587, 2025). "Both [177Lu]Lu-DOTA-CCK2R-dimer and mTOR inhibitor monotherapy and their combination effectively inhibited tumor growth." (PMID 40963930, 2025). "Autophagy is active in tumour cells, stimulated by intracellular stressors including mTOR inhibition, DNA damage, hypoxia and nutrient depletion." (PMID 40176088, 2025). "LP17-mediated TREM1 inhibition attenuated PMT through modulation of the TLR4/PI3K/AKT/mTOR pathway and reduced tumor growth in vivo." (PMID 41394801, 2025). "mTOR is a serine/threonine kinase that plays a role in tumor growth, angiogenesis, insulin resistance, fat creation, and other cellular processes, as well as in metabolism." (PMID 39823500, 2025). "Research indicates that targeting and inhibiting the PI3K/mTOR pathway can restore tumor cell sensitivity to palbociclib." (PMID 40206206, 2025). "S6K and RNF168, common downstream factors in the PI3K/Akt/mTOR pathway that influence tumor proliferation and migration, were significantly upregulated in mice treated with the AKT activator." (PMID 40328748, 2025). "The intricate crosstalk between ER signaling and other molecular pathways, such as PI3K/AKT/mTOR, underscores the need for innovative approaches to target endocrine resistance and tumor progression." (PMID 40299687, 2025). "CircNRIP1 is overexpressed in human GC tissues and acts as a sponge for miR-149-5p to trigger the AKT1/mTOR pathway, thus altering GC cell metabolism and promoting tumor progression." (PMID 40778324, 2025). "Increased HIF activation, which controls carcinogenesis, angiogenesis, and tumor expansion via VEGF, is generally associated with increased mTOR stimulation of following proteins, such as 70S6K and 4E‐BP1." (PMID 40717210, 2025). "Conversely, these genes exhibited inhibitory effects primarily in pathways related to growth signaling and cell survival, such as the RTK, PI3K/AKT and TSC/mTOR pathways, suggesting potential tumor-suppressive functions." (PMID 40002821, 2025). "Pathway enrichment analysis of metabolomic data revealed significant perturbations in arginine/proline metabolism, core tumor carbon metabolism, D-amino acid metabolism, mTOR signaling, branched-chain amino acid metabolism, and ascorbate metabolism." (PMID 41514605, 2025). "Conversely, leptin and resistin, which are pro-inflammatory adipokines, contribute to tumour-promoting processes by activating the PI3K/Akt/mTOR signalling pathway, thereby sustaining tumour cell survival, growth, and invasion." (PMID 41002741, 2025). "CMG002, a PI3K/mTOR bifunctional inhibitor, can be synergized with paclitaxel or cisplatin and has shown prominent tumor reduction, particularly in chemoresistant OC." (PMID 40075635, 2025). "Building on these findings, our results underscore the potential of targeting APOC1 to inhibit tumor angiogenesis by suppressing the PI3K/AKT/mTOR pathway." (PMID 39873475, 2025). "Parishin A exerts tumor-suppressive effects in OSCC through concurrent inhibition of the AKT/mTOR cascade." (PMID 41614860, 2025). "AMPK protects tumor cells from anoikis through suppression of protein synthesis via mTOR inhibition." (PMID 39735555, 2025). "Chronic inflammation, ongoing estrogen exposure, and oxidative stress in EM foster a tumor-friendly microenvironment where mTOR-driven pathways remain continuously activated." (PMID 40428769, 2025). "Colorectal cancer cell‐derived exosomes carrying miR‐21 inhibit PTEN, thereby activating the Akt/mTOR signalling pathway and enhancing tumour cell glycolysis and protein synthesis." (PMID 40525649, 2025).
tumor (continued). "Mutations of the TSC1 and TSC2 genes can affect the mechanistic target of the rapamycin (mTOR) signaling pathway and thus disrupt the regulating mechanisms of cell growth and proliferation, leading to tumor development." (PMID 40723161, 2025). "Inhibiting the PI3K/AKT/mTOR pathway has shown promise in reducing OSCC tumor growth and improving sensitivity to treatment." (PMID 39781358, 2025). "Among PI3K pathway inhibitors, BBB permeability remains a critical challenge with most mTOR inhibitors failing to effectively reach the tumor sites in the CNS." (PMID 40386392, 2025). "Temsirolimus also reduces the proliferation of glioma cells by blocking mTOR activity, and preclinical studies have also indicated its inhibitory effect on tumor growth, laying a foundation for further clinical research." (PMID 40149733, 2025). "Among its defining molecular alterations, PIK3CA mutations are frequently observed and are known to activate the PI3K/AKT/mTOR pathway, promoting tumor growth, survival, and endocrine resistance." (PMID 41425867, 2025). "IHC analysis elucidated alterations in intestinal barrier proteins, AKT1/mTOR pathway, and tumor proliferation and apoptosis biomarkers." (PMID 40919243, 2025). "PI3K/AKT/mTOR is a key regulatory pathway for FAO, and dysregulation of this pathway in tumor cells is closely associated with abnormal FAO metabolism." (PMID 40514365, 2025). "This enzyme activates the mTOR signaling pathway, further facilitating tumor metabolic reprogramming." (PMID 40520908, 2025). "GSVA analysis also found that C4_CD8-CD8A cells in the NT5E positive group were mainly enriched in pro-tumor pathways, such as PI3K_AKT_MTOR, angiogenesis, wnt_beta_catenin signal pathway." (PMID 41487509, 2025). "Compound 5e is a newly synthesized fluorescent molecule and a selective mTOR inhibitor by interacting with FKBP12 reducing tumor growth in human non-small cell lung cancer cells." (PMID 40248706, 2025). "In summary, the unique microenvironment of IR/MASH is not merely a passive background but actively engages in profound synergistic interactions with the aberrantly activated PI3K/Akt/mTOR signaling pathway within tumor cells." (PMID 41208895, 2025). "Tumor transcriptomic analysis revealed an over‐activation of the PI3K/AKT/mTOR and under‐activation of the DNA repair and JAK–STAT molecular circuits." (PMID 39876058, 2025). "IF enhances autophagy, lowers blood glucose and IGF-1 levels, and induces selective tumour cell death while preserving healthy cells, partly through modulation of the mammalian target of rapamycin (mTOR) and AMP-activated protein kinase (AMPK) pathways." (PMID 41335382, 2025). "Functionally, siANXA6 sensitizes CNE1R cells to 2 Gy irradiation, and CAL101 combination enhances tumor cell killing via PI3K/AKT/mTOR inhibition." (PMID 40725100, 2025). "AMPK affects not only glucose and lipid metabolism but also tumor bioenergetics by blocking the mammalian target of rapamycin (mTOR) pathway, which is critical for cell growth and division." (PMID 41439989, 2025). "In certain tumors, paradoxically, overactive mTOR signaling inhibits autophagy and facilitates tumor proliferation." (PMID 40710325, 2025). "The frequencies of genomic alterations involved in TCR-signaling/NF kappa-B, immune surveillance, PI3K/AKT/mTOR, and tumor suppressor were significantly higher in C2 than in the other subtypes." (PMID 40164718, 2025). "The metformin-activated AMPK signaling pathway reprograms metabolic processes of tumor cells, including protein and lipid biosynthesis via mTOR inhibition, thereby inhibiting tumor growth." (PMID 39776799, 2025). "Intratumoural Escherichia-Shigella- and Enterobacteriaceae-derived LPS promoted NSCLC progression via the TLR4-mTOR-NF-κB-IL-6 axis, whereas the addition of the mTOR inhibitor rapamycin significantly suppressed LPS-induced tumor proliferation." (PMID 40817754, 2025).